TRAV30 (T cell receptor alpha variable 30)
Description:
V region of the variable domain of T cell receptor (TR) alpha chain that participates in the antigen recognition. Alpha-beta T cell receptors are antigen specific receptors which are essential to the immune response and are present on the cell surface of T lymphocytes. Recognize peptide-major histocompatibility (MH) (pMH) complexes that are displayed by antigen presenting cells (APC), a prerequisite for efficient T cell adaptive immunity against pathogens. Binding of alpha-beta TR to pMH complex initiates TR-CD3 clustering on the cell surface and intracellular activation of LCK that phosphorylates the ITAM motifs of CD3G, CD3D, CD3E and CD247 enabling the recruitment of ZAP70. In turn ZAP70 phosphorylates LAT, which recruits numerous signaling molecules to form the LAT signalosome. The LAT signalosome propagates signal branching to three major signaling pathways, the calcium, the mitogen-activated protein kinase (MAPK) kinase and the nuclear factor NF-kappa-B (NF-kB) pathways, leading to the mobilization of transcription factors that are critical for gene expression and essential for T cell growth and differentiation. The T cell repertoire is generated in the thymus, by V-(D)-J rearrangement. This repertoire is then shaped by intrathymic selection events to generate a peripheral T cell pool of self-MH restricted, non-autoaggressive T cells. Post-thymic interaction of alpha-beta TR with the pMH complexes shapes TR structural and functional avidity.
Synonyms: TCRAV29S1; TCRAV30S1
Gene: T-cell receptor variable (V) gene on chromosome 14 (22,168,429 to 22,168,988, forward strand). Ensembl gene ENSG00000259092.
Subcellular location: Cell membrane
Gene Ontology:
Biological process: response to bacterium
Cellular component: plasma membrane
Homologues: Orthologues: macaque TRAV30 (72% identical). Paralogues in human: TRAV34 (57% identical), TRAV25 (41% identical), TRAV27 (38% identical), TRAV20 (37% identical), TRAV17 (36% identical), TRAV21 (33% identical), TRAV24 (33% identical), TRAV10 (32% identical), TRAV36DV7 (30% identical), TRAV39 (30% identical), TRAV6 (30% identical), TRAV7 (30% identical), and 11 more.
Diseases named in the same sentence as TRAV30 in open-access papers:
TRAV30 is named in the same sentence as 2 diseases in open-access papers, as found by Europe PMC text mining. Sharing a sentence is not in itself a finding about the gene and the disease.
TRAV30 shares sentences with these, for which no sentence is quoted: COVID-19 (1 paper); endometrial cancer (1).